PIP4K2B (phosphatidylinositol-5-phosphate 4-kinase type 2 beta)
Description:
Participates in the biosynthesis of phosphatidylinositol 4,5-bisphosphate. Preferentially utilizes GTP, rather than ATP, for PI(5)P phosphorylation and its activity reflects changes in direct proportion to the physiological GTP concentration. Its GTP-sensing activity is critical for metabolic adaptation. PIP4Ks negatively regulate insulin signaling through a catalytic-independent mechanism. They interact with PIP5Ks and suppress PIP5K-mediated PtdIns(4,5)P2 synthesis and insulin-dependent conversion to PtdIns(3,4,5)P3.
Synonyms: PIP5K2B; PIP5KIIB; PIP5KIIbeta; PI5P4KB; PIP5P4KB
Tractability: Small molecule: a structure with a bound ligand is known; a high-quality ligand is known; it has a high-quality binding pocket; it belongs to a druggable protein family. Antibody: its Gene Ontology location is reachable by antibodies, with high confidence; UniProt places it where antibodies can reach, with medium confidence. PROTAC: UniProt records ubiquitination sites on it; ubiquitination databases record sites on it; its protein half-life has been measured; a small molecule that binds it is known.
Target class: Kinase; Enzyme
Chemical probes: THZ-P1-2 (high quality), TM-04-176-01 (high quality)
Safety:
Unwanted effects reported when the protein is acted on. In parentheses: how it was acted on, where the effect was seen, and who reports it.
cardiac arrhythmia (cardiovascular system; source: Lamore et al. (2017))
Gene: Protein-coding gene on chromosome 17 (38,765,691 to 38,800,126, reverse strand). Ensembl gene ENSG00000276293.
Subcellular location: Endoplasmic reticulum membrane; Cell membrane; Nucleus; Cytoplasm
Subcellular location (Human Protein Atlas): Nucleoplasm
Pathways (Reactome):
Metabolism: Synthesis of PIPs at the plasma membrane; Synthesis of PIPs in the nucleus
Signal Transduction: PI5P, PP2A and IER3 Regulate PI3K/AKT Signaling
Gene Ontology:
Molecular function: 1-phosphatidylinositol-4-phosphate 5-kinase activity; ATP binding; GTP binding; protein binding; protein homodimerization activity; 1-phosphatidylinositol-5-phosphate 4-kinase activity; phosphatidylinositol kinase activity
Biological process: 1-phosphatidyl-1D-myo-inositol 4,5-bisphosphate biosynthetic process; negative regulation of insulin receptor signaling pathway; positive regulation of autophagosome assembly; regulation of autophagy; autophagosome-lysosome fusion; cell surface receptor signaling pathway; phosphatidylinositol phosphate biosynthetic process; phosphatidylinositol metabolic process
Cellular component: autophagosome; cytoplasm; nucleoplasm; nucleus; plasma membrane; cytosol; endoplasmic reticulum membrane
Genetic constraint (gnomAD): Loss-of-function variants: 2 observed, 28.14 expected, observed/expected ratio (o/e) 0.0711, 90% interval 0.028 to 0.22. The upper end of that interval is the gene's LOEUF score, 0.22, which puts it in group 1 of 6, group 1 being the genes least tolerant of losing a copy. Missense variants: 269 observed, 451.55 expected, observed/expected ratio (o/e) 0.6, 90% interval 0.54 to 0.66. Synonymous variants: 167 observed, 172.83 expected, observed/expected ratio (o/e) 0.97, 90% interval 0.85 to 1.1.
Homologues: Orthologues: chimpanzee PIP4K2B (100% identical), macaque PIP4K2B (100% identical), dog PIP4K2B (99% identical), mouse Pip4k2b (99% identical), pig PIP4K2B (99% identical), rabbit PIP4K2B (94% identical), rat Pip4k2b (93% identical), tropical clawed frog pip4k2b (91% identical), guinea pig PIP4K2B (85% identical). Paralogues in human: PIP4K2A (76% identical), PIP4K2C (64% identical), PIP5K1A (33% identical), PIP5K1B (32% identical), PIP5K1C (31% identical), PIP5KL1 (20% identical).
Diseases named in the same sentence as PIP4K2B in open-access papers:
PIP4K2B is named in the same sentence as 20 diseases in open-access papers, as found by Europe PMC text mining. Sharing a sentence is not in itself a finding about the gene and the disease. The quoted sentences say what the papers report.
breast carcinoma (7 papers, 2010 to 2024). "For PIP4K2B, both excessively high and low levels are implicated in breast cancer and patient survival." (PMID 38156113, 2023). "We also identified PIP4K2B (phosphatidylinositol 5-phosphate 4-kinase type-2 beta), of which a low expression has been associated with low survival, high grade, and increased tumor size in breast cancer." (PMID 29681787, 2018). "PIP4K2B, known for its frequent amplification and oncogenic role in breast cancer, also plays a role in lymphoma and sarcoma." (PMID 38539515, 2024). "Overexpression of PIP4K2B can increase breast cancer cell proliferation and anchorage-independent growth in different subsets of breast cancer cell lines." (PMID 38156113, 2023). "The same study investigated the role of PIP4K2B in regulating the growth of breast cancer cells, and the knockdown of PIP4K2B induces EMT characteristics in breast cancer cells." (PMID 31488171, 2019). "Additionally, HER2+ breast cancer samples generally overexpress both PIP4K2B and PIP4K2A." (PMID 32230859, 2020). "It has been reported that low PIP4K2B expression was correlated with increased distant metastasis and with worse prognosis in breast cancer, implying that PIP4K2B may be a tumor suppressive factor in breast cancer." (PMID 31488171, 2019).
pancreatic cancer (4 papers, 2019 to 2021). "In addition, lncRNA PXN-AS1 repressed cell growth by reducing miR-3064-5p and upregulating phosphatidylinositol-5-phosphate 4-kinase type 2 beta (PIP4K2B) expression in pancreatic cancer." (PMID 34672237, 2021).
Insulin resistance (3 papers, 2017 to 2025). Increased resistance towards insulin, that is, diminished effectiveness of insulin in reducing blood glucose levels. "If the enhanced ER localization and activity of PIP4k2b underlies MANF-mediated insulin resistance, reducing PIP4k2b should alleviate the impaired insulin response." (PMID 28924165, 2017). "Another hit, PIP4K2B, plays a role in insulin resistance and promotes tumorigenesis by regulating PI3K signaling, a pathway which is known to inhibit Hippo." (PMID 40869130, 2025). "It has previously been shown that MANF triggers insulin resistance by enhancing the activity of phosphatidylinositol 5-phosphate 4-kinase type-2 beta (PIP4k2b, a kinase known to regulate insulin signaling) localized to the endoplasmic reticulum." (PMID 34220710, 2021). "It has been shown that MANF interacts with PIP4k2b and triggers insulin resistance via an unknown pathway other than the inflammatory activation state." (PMID 34220710, 2021). "These previous findings provided us a strong rational to investigate whether increased MANF augments PIP4k2b function to yield insulin resistance." (PMID 28924165, 2017). "Moreover, MANF triggers hypothalamic insulin resistance by enhancing the ER localization and activity of PIP4k2b, a kinase known to regulate insulin signaling." (PMID 28924165, 2017).
Lung Fibrosis (3 papers, 2023 to 2025). "Autoantibodies against PIP4K2B and AKT3 are increased risk of skin and lung fibrosis in patients with SSc." (PMID 40843700, 2025). "Autoantibodies against PIP4K2B and AKT3 show increased risk of skin and lung fibrosis in patients with SSc." (PMID 40843700, 2025). "Additional autoantibodies against anti-phosphatidylinositol-5-phosphate 4-kinase type 2 beta (PIP4K2B) and AKT serine/threonine kinase 3 (AKT3) have been linked to increased pulmonary fibrosis in SSc." (PMID 37886934, 2023). "Anti-Phosphatidylinositol-5-phosphate 4-kinase type 2 beta (PIP4K2B)- and anti-AKT Serine/Threonine Kinase 3 (AKT3)-antibodies should be further explored to confirm their association with skin and lung fibrosis in SSc patients." (PMID 36982700, 2023).
head and neck cancer (1 paper, 2024). A primary or metastatic malignant neoplasm affecting the head and neck. "We found that PIP4K2B positively regulates the mTOR signaling pathway and promotes head and neck cancer cell growth." (PMID 38539515, 2024). "This means that PIP4K2B plays different roles in head and neck cancer cells depending on their site of origin." (PMID 38539515, 2024). "This study identified the PIP4K2B protein as a key target of NSD1 in head and neck cancer." (PMID 38539515, 2024). "Since PIP4K2B affects PI3K and mTORC1 signaling, and as we recently showed that NSD1 depletion decreases Akt/mTORC1 signaling, we investigated whether mTORC1 regulation could be PIP4K2B-dependent in head and neck cancer." (PMID 38539515, 2024).
laryngeal carcinoma (1 paper, 2024). Carcinoma that arises from the laryngeal epithelium. "NSD1 and PIP4K2B have potential as targets for laryngeal cancer therapy and future cancer drug development." (PMID 38539515, 2024). "We conclude that PIP4K2B is a promising target for HNSCC therapy, especially in laryngeal carcinoma subtype." (PMID 38539515, 2024). "In conclusion, our findings implicate PIP4K2B as a novel NSD1-dependent protein in HNSCC, suggesting its potential significance for laryngeal cancer cell survival." (PMID 38539515, 2024). "Moreover, the overexpression of PIP4K2B in NSD1-depleted cells leads to the restoration of proliferation levels and downstream targets of mTORC1, specifically observed in a laryngeal cancer cell line." (PMID 38539515, 2024).
lymph node metastasis (1 paper, 2019). "We observed that increased tumor size, advanced TNM stage and the presence of lymph node metastasis were associated with reduced PIP4K2B expression in PC patients." (PMID 31488171, 2019).
prostate adenocarcinoma (1 paper, 2023). "PIP4K2A, PIP4K2B, and PIP4K2C transcript expression was detected in clinically localized [The Cancer Genome Atlas (TCGA)-Prostate Adenocarcinoma (PRAD), N = 498] and advanced, metastatic PCa [Stand Up 2 Cancer-Prostate Cancer Foundation (PCF) (SU2C, N = 209)] datasets." (PMID 36724278, 2023).
tumor (9 papers, 2016 to 2025). "Based on the results obtained from the NDEx analysis through Cytoscape.org, genes such as PIP4K2B were assigned to metabolic reprogramming, an emerging hallmark that highlights how cancer cells adapt their metabolism to support tumor growth." (PMID 40136626, 2025). "Low PIP4K2B expression associates with increased tumor size and distant metastasis, whereas high PIP4K2B expression strongly associates with ERBB2 expression." (PMID 27895661, 2016). "We also analyzed the expression of PIP4K2B in PC samples classified by histological pathological stage and tumor grade using the UALCAN database." (PMID 31488171, 2019). "When PCs were categorized by tumor grades, PIP4K2B expression was progressively downregulated in tumors with advanced grades." (PMID 31488171, 2019). "Therefore, we demonstrate that PIP4K2B acts as a tumor suppressor and a functional downstream effector of miR-3064 in PC cells." (PMID 31488171, 2019). "In our current study, the introduction of PIP4K2B reversed the tumor-promoting effects of miR-3064 in PC cells, suggesting that the gain of miR-3064 expression could result in the attenuation of tumor suppressor PIP4K2B, resulting in enhanced PC progression." (PMID 31488171, 2019).
cancer (7 papers, 2016 to 2025). A tumor composed of atypical neoplastic, often pleomorphic cells that invade other tissues. "In conclusion, our study contributes to advancing our understanding of the role of PIP4K2B in cancer and underscores the significance of K36me2 histone methyltransferases in HNSCC." (PMID 38539515, 2024). "The product is involved in regulation of cell proliferation, and overexpression of PIP4K2B can be contribute to cancer." (PMID 29361907, 2018). "Given that PIP4Ks are potential targets for cancer treatment, we investigated whether PIP4K2B depletion affects proliferation in HNSCC cell lines." (PMID 38539515, 2024). "Among these proteins, we have identified many differentially abundant proteins identified as having a role in cancer (IFIT1, FASTKD2, PIP4K2B, ARID1B, SLC25A33: overexpressed in TR; CALD1, CPA3, B3GALT5, CD177, RIPK1: overexpressed in NR)." (PMID 29681787, 2018). "We have identified many differentially abundant proteins already identified as having a role in cancer, such as the earlier discussed proteins IFIT1, FASTKD2, PIP4K2B, ARID1B and SLC25A33 (more abundant in TR) or CALD1, CPA3, B3GALT5, CD177 and RIPK1 (more abundant in NR)." (PMID 29681787, 2018). "According to COSMIC, other interesting cancer related genes are present in these top lists, such as EPHA5, which belongs to the ephrin receptor subfamily of the protein-tyrosine kinase family and PIP4K2B, an enzyme that catalyzes phosphorylation, showing kinase activities." (PMID 27895661, 2016).
infection (2 papers, 2022 to 2025). The state of being infected such as from the introduction of a foreign agent such as serum, vaccine, antigenic substance or organism. "In this study, we found MCL1 and PIP4K2B proteins upregulated after PAstV/SH/2022/CM1 infection, which were related to autophagy." (PMID 35891364, 2022). "In view of the close relationship of NLRX1, VPS25, and PIP4K2B with mitophagy, we speculate that PAstV/SH/2022/CM1 infection may cause mitochondrial injury—mitophagy—to resist the innate host immunity." (PMID 35891364, 2022). "Western blot analysis revealed that WT STM infection specifically enhances PI5P4K2A but not the PIP4K2B isoform." (PMID 39695325, 2025).
PIP4K2B also shares sentences with these, for which no sentence is quoted: breast tumor (1 paper); head and neck squamous cell carcinoma (1); invasive breast carcinoma (1); lung adenocarcinoma (1); lymphoma (1); prostate carcinoma (1); sarcoma (1); systemic sclerosis (1); virus infection (1).